INS (insulin)
Diseases named in the same sentence as INS in open-access papers (continued):
Sharing a sentence is not in itself a finding about the gene and the disease.
Insulin resistance (continued). "Fasting serum insulin and homeostasis model assessment of insulin resistance (HOMA-IR) were significantly higher in the group with obesity (P < 0.05)." (PMID 36570168, 2022). "Reduced sensitivity of cells to insulin is termed insulin resistance, which often occurs in obesity and related T2DM." (PMID 36465655, 2022). "Homeostasis model assessment-estimated insulin resistance (HOMA-IR) is a mathematical model that includes interactions between fasting plasma insulin and fasting plasma glucose concentrations." (PMID 36559252, 2022). "Insulin resistance (IR) is a disordered biological response for insulin stimulation through the disruption of different molecular pathways in target tissues." (PMID 35794109, 2022). "Tumor necrosis factor alpha (TNF-α), which is a pro-inflammatory cytokine, can destroy the tyrosine phosphorylation activation of IR and IR substrate (IRS) in the insulin signaling cascade, thereby leading to insulin resistance." (PMID 35846289, 2022). "It is clearly demonstrated that changes in FoxO activity have a repressive effect on insulin signaling in cardiomyocytes through inhibition of protein phosphatases, which led to Akt activation, reduced insulin resistance and impaired glucose metabolism." (PMID 35351872, 2022). "In patients with insulin resistance, such as in obesity and type 2 diabetes, it is thought that insulin signaling via the MAPK pathway is preserved, in contrast to impairment of the PI3K/AKT pathway, promoting more growth and proliferation effects." (PMID 35158824, 2022). "Clinical parameters including lipids profile, serum creatinine, cystatin C, fasting glucose, insulin and C-peptide levels, HbA1c values and insulin resistance (HOMA-IR) were assessed in patients with ALMS and BBS." (PMID 36506055, 2022). "Second, circadian disruption and eating meals irregularly disturb the natural rhythmicity of insulin action and lead to insulin resistance and obesity." (PMID 35690716, 2022). "On a mechanistic basis, excess adipose causes adipocytes to hypertrophy and induces a configurational membrane change that interferes with the function of glucose transporters, resulting in increased insulin, or insulin resistance." (PMID 35444916, 2022). "Insulin resistance was characterized by acanthosis nigricans, as well as by high serum levels of fasting insulin (358.3 pmol/L) and C-peptide (2.2 nmol/L), as well as by the low levels of total serum adiponectin (<0.01 mg/L)." (PMID 35341481, 2022). "A few studies have confirmed Nrf2 is related to insulin signaling and insulin resistance due to its crucial cytoprotective, ROS scavenging, and anti-inflammatory roles." (PMID 36290791, 2022). "It stimulates glycolysis, improving insulin secretion, and inhibits gluconeogenesis and adipogenesis in the liver; by reducing insulin resistance, berberine also improves ovulation." (PMID 35209140, 2022). "It implies that the effect of LJF on the imbalance of insulin resistance and insulin sensitivity can be in a certain dose-dependent manner." (PMID 36613249, 2022). "It has long been appreciated that an increased adipocyte size correlates to systemic insulin resistance, while smaller adipocytes retain insulin sensitivity." (PMID 35163825, 2022). "Consistently, the higher contents of SDS and RS of the EDA offers a favorable dietary formula to lower insulin-reduced lipidemic response following food ingestion, alleviating insulin resistance and thereby reducing TC and TG in the long term." (PMID 35205970, 2022). "There is evidence that the HOMA-IR is a useful test for the evaluation of IR, even in patients with T2DM treated with exogenous insulin, which is why we analyzed insulin resistance using the HOMA-IR index." (PMID 35454146, 2022). "In vitro models of adipocytes are crucial to understand molecular mechanisms of adipogenesis, the development of insulin sensitivity, the pathogenesis of insulin resistance, and the regulation of adipokine expression and secretion." (PMID 35986215, 2022).
Insulin resistance (continued). "Pooled estimate of nine papers indicated a significant reduction of fasting insulin (FI) (p = 0.006), and homeostasis model assessment of insulin resistance (p = 0.0001)." (PMID 36278155, 2022). "Cigarette smoking also induces insulin resistance, thereby corroborating the presence of insulin requirements in these patients." (PMID 35836916, 2022). "In a meta-analysis in 2020, nine studies on the effects of probiotics on neurological diseases were analyzed, showing that probiotics had a significant positive effect on insulin, insulin resistance, triglycerides, and VLDL and HDL cholesterol." (PMID 35685534, 2022). "There was an increase in insulin secretion as assessed by oral disposition index, a reduction in insulin resistance (HOMA-IR), and serum total cholesterol levels relative to the control group participants." (PMID 36704786, 2022). "The advanced, long-term type 2 diabetes with poor glycaemic control is often characterised by high blood glucose and lowering insulin levels and severe insulin resistance." (PMID 35090539, 2022). "While systemic loss of T-bet protected against the development of insulin resistance, the ablation of IFNγ, the major TH1 cytokine, only modestly improved insulin sensitivity in obese mice." (PMID 34837070, 2022). "HQLHS significantly decreased the levels of fasting blood glucose, fasting insulin, and homeostasis model assessment-insulin resistance (HOMR-IR) and increased liver glycogen content." (PMID 36312936, 2022). "Insulin resistance is indicated by increased fasting glucose, plasma insulin levels, and HOMA-IR in the DEX group compared to the control group." (PMID 35565871, 2022). "IRS-1 and IRS-2 regulate insulin-dependent hepatic glucose metabolism, and their dysregulation contributes to insulin resistance and type 2 diabetes." (PMID 36290594, 2022). "While another concept is that decreased insulin secretion and insulin resistance increase lipolysis, contributing to the development of MAFLD." (PMID 36148775, 2022). "In most obese people, insulin resistance is paralleled by increased blood insulin levels, likely a compensatory factor." (PMID 35335211, 2022). "Increasing insulin sensitivity and improving insulin resistance are crucial to maintain glucose homeostasis in diabetic patients." (PMID 35927761, 2022). "The resulting insulin resistant mice were used in the rescue stage to test the capacity of STX4 enrichment to reverse insulin resistance." (PMID 35058456, 2022). "When excess fat is deposited over the liver, the onset of hepatic insulin resistance and then systemic insulin resistance is expected." (PMID 35276886, 2022). "To validate the mechanism of insulin resistance via glucose levels’ tolerance to high insulin, we measured the mRNA expression genes at insulin-signaling levels such as akt and pepck genes." (PMID 35955446, 2022). "Reduced mitochondrial activity was observed in human insulin-resistant skeletal muscle, and conversely abnormal mitochondrial function resulted in insulin resistance and T2D." (PMID 36358481, 2022). "Serum glypican-4 (GPC4) has been identified as an insulin-sensitizing adipokine serving as a marker for body mass index and insulin resistance in humans." (PMID 35715556, 2022). "Typically, insulin resistance is considered as a decrease in sensitivity or responsiveness to the metabolic actions of insulin including insulin-mediated glucose disposal." (PMID 36176638, 2022). "Other potential links include insulin resistance due to insulin signaling impairment, which is also observed in prediabetes, inflammation or oxidative stress alterations." (PMID 36345028, 2022). "Chronic inflammation and increased oxidative stress stimulate insulin resistance and also deprive retinal cells of neurotrophic factors essential for their survival, including insulin, leukemia inhibitory factor, and ciliary neurotrophic factor." (PMID 35476846, 2022).
Insulin resistance (continued). "Gene expression and circulating leptin levels were reported to be increased by insulin; thus, the insulin resistance in PCOS patients is suggested to elevate leptin secretion from WAT." (PMID 36289764, 2022). "MAFLD patients were younger, had shorter diabetic duration, and had greater BMI, aspartate aminotransferase (AST), alanine aminotransferase (ALT), fasting insulin, postprandial insulin, total cholesterol, and insulin resistance levels (HOMA-IR and TyG index)." (PMID 35127953, 2022). "Dietary interventions are successful in treating the associated risk factors of metabolic syndrome, including the reversal of insulin resistance, increasing insulin sensitivity, treating hypertension, and reducing body weight." (PMID 36017333, 2022). "Insulin resistance (IR) is a condition characterized by a subnormal physiological response to normal insulin concentrations, with increased amounts of insulin produced to maintain adequate intracellular glucose concentrations." (PMID 35976296, 2022). "Studies report that PTEN impairs insulin signaling and induces insulin resistance during the pathogenesis of type 2 diabetes." (PMID 35726320, 2022). "Multiple modalities exist for treating hyperglycemia and/or insulin resistance in T2D, which can either increase insulin release or relieve the secretory burden of the β-cell." (PMID 35204835, 2022). "Insulin resistance (IR) can be defined as a pathological condition of cellular insulin signaling impairment with consequent disturbance of intracellular signaling transduction, which affects several organs and tissues." (PMID 35574036, 2022). "An impaired compensatory increase in insulin secretion to overcome the pregnancy-induced insulin resistance characterizes this disease." (PMID 35090536, 2022). "Activation of inactivation of these major proteins through phosphorylation or dephosphorylation plays a role in aggravating insulin signaling abnormalities that lead to insulin resistance." (PMID 36355489, 2022). "The levels of insulin and insulin resistance (HOMA-IR) of group N were higher than those of the other groups (p < 0.05), and the FEO-inhaled groups were significantly lower than those of the H group (p < 0.05)." (PMID 35215391, 2022). "In diabetic patients and in animals with insulin resistance, PPARγ improves both glucose tolerance and cellular insulin sensitivity." (PMID 36233271, 2022). "Pro‐inflammatory cytokines interfere with insulin signaling related to insulin resistance in women with GD resulting in increased inflammatory markers such as C‐reactive protein." (PMID 35243684, 2022). "In our study Osteocalcin alleviated insulin resistance, reduced hyperinsulinemia and enhanced insulin action in type 2 diabetes patients." (PMID 36307866, 2022). "Increased serum insulin secretion and insulin resistance are the most obvious maternal metabolic changes." (PMID 36246890, 2022). "The impaired recruitment of GLUT4 for increased glucose transport in response to insulin is one of the characteristics of clinical insulin resistance." (PMID 35216280, 2022). "The majority of the patients suffered from T2DM, with high serum glucose, HbAc and altered insulin profile with insulin resistance." (PMID 35455702, 2022). "Insulin resistance occurs when increasing levels of insulin are required to exert a biological effect in the target tissues, and in particular adipose tissue and skeletal muscle." (PMID 35964329, 2022). "Evidence obtained both in the experimental and clinical setting clearly indicates that insulin promotes renal sodium retention leading to volume expansion, an effect that is preserved in states of metabolic insulin resistance." (PMID 36289636, 2022). "East Asian and American show different pathophysiology of T2DM, East Asian shows low insulin secretion ability and insulin resistance with mild obesity." (PMID 35672759, 2022).
Insulin resistance (continued). "A preclinical study was conducted to evaluate the effects of TTI on fasting glucose, insulinemia, insulin resistance indexes, pancreatic β cell functionality and insulin sensitivity using a diet-induced T2DM model." (PMID 35892791, 2022). "It has been found that exosomes affect insulin secretion and the regulation of insulin resistance through various pathways." (PMID 36187097, 2022). "When peripheral tissues develop insulin resistance, the pancreas generates more insulin to counteract the condition." (PMID 35840638, 2022). "IRS1 and IRS2 are vital components of insulin signaling, and the loss of IRS1 and IRS2 mediates insulin resistance." (PMID 35454166, 2022). "Insulin resistance measured by the blood glucose and insulin levels was higher in untreated PCOS-EC mice than in those treated with Diane-35 and metformin." (PMID 35052471, 2022). "Insulin resistance is a reduced response of the skeletal muscle, white adipose tissue, and liver to the biological effect of insulin." (PMID 36093112, 2022). "Subjects who develop T2D have a complex phenotype with defects in insulin secretion and insulin resistance in target tissues." (PMID 39086962, 2022). "Conversely, liver-specific IDE knockout (L-IDE-KO) mice fed a high-fat diet (HFD) showed insulin resistance and glucose intolerance accompanied by elevated fasting insulin levels." (PMID 35017319, 2022). "The product of fasting insulin and glucose levels, which reflects insulin resistance, was marginally higher in sham-operated WT and 5xFAD mice." (PMID 36033613, 2022). "Conceptualizing the relationship between adrenal incidentalomas and insulin resistance requires an appreciation of the role of insulin." (PMID 35457158, 2022). "In type 2 diabetes (T2D), hyperglycemia results from insulin resistance and reduced or insufficient compensatory insulin production." (PMID 35303528, 2022). "In turn, this pro-inflammatory state directly impacts insulin signaling, promoting insulin resistance." (PMID 36550567, 2022). "Insulin resistance (IR), defined as the attenuation of insulin responsiveness in tissues, is a crucial mechanism in glycolipid metabolism." (PMID 35370984, 2022). "On the contrary, people with obesity and, especially, with AO, develop insulin resistance and the level of insulin and C-peptide in the blood increases." (PMID 36579566, 2022). "Insulin resistance manifests as an inability of insulin to facilitate glucose uptake and utilization in the body." (PMID 35774142, 2022). "In general, insulin resistance plays a key role in liver lipid imbalance, and the accumulation of TG in the liver will aggravate liver insulin resistance, thereby increasing insulin-antagonistic cytokines." (PMID 35402467, 2022). "Chronic inflammation increases insulin resistance in insulin‐sensitive organs, such as the liver and skeletal muscles, and leads to impaired glucose tolerance." (PMID 36162824, 2022). "Methods of assessing insulin resistance exist, such as the Pancreatic Suppression Test, Insulin Suppression Test, Glucose Clamp, and Hyperinsulinemic-Euglycemic Clamp Technique." (PMID 36345438, 2022). "Once insulin resistance occurs, the pancreas will increase insulin to compensate, and fasting plasma insulin levels increase." (PMID 36009505, 2022). "Candida albicans is a conditional pathogen and as a significant indirect factor induces increased insulin secretion and insulin resistance." (PMID 36397429, 2022). "Hepatic insulin resistance decreases liver response to insulin signaling by interrupting the insulin-induced inhibition of hepatic glucose production, which leads to hyperlipidemia, hyperglycemia, liver disease, and type 2 diabetes." (PMID 36235710, 2022). "Impaired insulin secretion and/or insulin resistance were estimated to affect 425 million patients worldwide in 2017, with 90% of the patients having a diagnosis of T2DM." (PMID 35615716, 2022).
Insulin resistance (continued). "Increased levels of PTX3 were found in obese patients and in conditions of elevated insulin levels characteristic of insulin resistance, such as metabolic syndrome and DM." (PMID 35887276, 2022). "Considering the diabetic offspring, the OD/SD and OD/HFD rats had higher fasting glucose levels and AUC, confirming intolerance glucose status and higher insulin concentrations, confirming insulin resistance." (PMID 35706903, 2022). "A primary characteristic of T2D is insulin resistance, where tissues such as skeletal muscle, liver and adipose tissue become resistant to circulating peripheral insulin." (PMID 36555450, 2022). "By increasing glucose utilization, reducing insulin resistance and enhancing insulin sensitivity, metformin is helpful to reduce blood glucose." (PMID 35721320, 2022). "Tumor necrosis factor inhibits skeletal myocyte differentiation, promotes muscle atrophy, and contributes to insulin resistance by impairing the insulin signaling pathway." (PMID 35463384, 2022). "In fact, treatment of mice with SecinH3 induced hepatic insulin resistance by altering the insulin-regulated expression of various genes related to gluconeogenesis, glycolysis, and fatty acid synthesis in the liver." (PMID 35563476, 2022). "Despite this, our animal model displayed other features of T2DM such as hyperglycaemia, hyperinsulinaemia, impaired glucose tolerance, decreased insulin sensitivity and cardiac insulin resistance." (PMID 35365882, 2022). "As a result of this insulin resistance, the pancreas first enters into a “compensatory period” in which β-cells hypertrophy and produce more insulin." (PMID 35327570, 2022). "T2D is characterized by defective insulin secretion and insulin resistance, which leads to postprandial and fasting hyperglycemia, dyslipidemia, and hyperinsulinemia." (PMID 36145191, 2022). "Peripheral insulin resistance decreases insulin signaling in the central nervous system, that is, central insulin resistance, which disrupts brain metabolism and increases Aβ toxicity." (PMID 36203845, 2022). "Derangement of intracellular GLUT4 behavior and defects in insulin signaling are suggested to be etiologically related to insulin resistance." (PMID 35434546, 2022). "The genetic model showed a reduction in circulating insulin by ~25% improved systemic insulin resistance and extended the lifespan in mice." (PMID 35012677, 2022). "These in vitro and animal studies are supported by the observation that DHA-rich fish oil reduced fasting insulin in humans with hyperinsulinemia and insulin resistance." (PMID 36778598, 2022). "Visceral fat accumulation induces the secretion of pro-inflammatory cytokines, including IL-6, TNF-α, and IL-8, which reduces insulin sensitivity and leads to hyperinsulinemia and even insulin resistance." (PMID 36474704, 2022). "Another study reported that the effects of NS on fasting insulin and insulin resistance in newly diagnosed patients with T2DM were comparable to the standard oral hypoglycaemic agent (OHA) metformin following treatment for 3 months." (PMID 36438767, 2022). "Oxidative stress plays a role in the development of insulin resistance by interrupting insulin signaling pathways and dysregulating adipocytokines." (PMID 36242012, 2022). "Insulin resistance is defined as an impaired biologic response to insulin stimulation in target tissues, primarily the liver, muscle, and adipose tissue." (PMID 35455055, 2022). "In another instance, deleting glutamate dehydrogenase in beta-cells reduces the amplification of glucose stimulated insulin secretion (GSIS) and thus protects against insulin resistance caused by HFD." (PMID 34823065, 2022). "Disturbances in adipocytokine secretion by adipose tissue contributing to both insulin resistance and impairment of insulin production are frequently described in metabolic diseases such as obesity and T2D." (PMID 36614099, 2022).